DDIT3 (DNA damage inducible transcript 3)
Diseases named in the same sentence as DDIT3 in open-access papers (continued):
Sharing a sentence is not in itself a finding about the gene and the disease.
myxoid liposarcoma (continued). "This suggests that NF-kappaB (p50) transcription in myxoid liposarcoma might be regulated by the FUS/DDIT3 fusion gene." (PMID 20863376, 2010). "Of note, since the comparison group consisted mostly of tumors with myxoid stroma and/or adipocytic differentiation, rather than tumors with round cell morphology, further studies may be warranted to confirm the specificity of DDIT3 expression in mimics of high-grade myxoid liposarcoma." (PMID 33921435, 2021). "Fluorescence in situ hybridization (FISH) for DDIT3/GLI1 (12q13.3) was within the reference range, ruling out myxoid liposarcoma." (PMID 40084340, 2025). "Myxoid liposarcoma (MLS) accounts for 20%-30% of all liposarcomas, with most cases harboring the fusion gene FUS::DDIT3, while approximately 5% exhibit the EWSR1::DDIT3 fusion." (PMID 41108625, 2025). "In this case, the FISH study for DDIT3/GLI1 was within the reference range, which is more relevant for excluding myxoid liposarcoma." (PMID 40084340, 2025). "The interactions of DDIT3 with the SWI/SNF CRC subunits BAF155 and INI1 in the myxoid liposarcoma cell line were confirmed." (PMID 40065228, 2025). "Myxoid liposarcoma (MLS) displays a distinctive tumor microenvironment and is characterized by the FUS::DDIT3 fusion oncogene, however, the precise functional contributions of these two elements remain enigmatic in tumor development." (PMID 38671504, 2024). "Identifying DDIT3 rearrangement using FISH break‐apart probes is a sensitive and specific strategy for the diagnosis of myxoid liposarcoma." (PMID 34984861, 2022). "mir-616 and mir-28 are derived from transposed elements (LINE, L2 family) and are located within two translocation breakpoints, respectively DDIT3, that is often fused to FUS in myxoid liposarcoma, and LPP, that is fused to MLL in a secondary acute leukemia." (PMID 20567512, 2010). "Both fusion proteins FUS-DDIT3 and EWSR1-FLI1 were shown to interact with the SWI/SNF CRCs in MLS 402-91 (myxoid liposarcoma) or EWS TC‐71 (Ewing sarcoma) cell lines, with each line carrying different FET oncogenes with simultaneous lack of expression of normal DDIT3 or FLI1." (PMID 40065228, 2025). "Split-signal FISH results negative for significant DDIT3 signal splitting ruled against myxoid liposarcoma." (PMID 34797454, 2021). "Myxoid liposarcoma, however, often harbors rearrangement involving the DDIT3 gene, which is not present in PPMS." (PMID 32039736, 2020). "Molecular testing, either for rearrangements involving CHOP/DDIT3 by fluorescence in-situ hybridization assay or reverse polymerase chain reaction for the specific fusion transcripts, can also be helpful in confirming the diagnosis of myxoid liposarcoma." (PMID 23272660, 2012). "The vast majority of myxoid liposarcomas exhibit no DDIT3 expression." (PMID 40710010, 2025). "Indeed, this last classification includes also new entities, such as myxoid pleomorphic liposarcoma, a myxoid liposarcoma with non-specific karyotype and lacking the classical gene fusion of DDIT3 with FUS or ESWR1." (PMID 34299136, 2021). "Reporter assays showed that the EWSR1-DDIT3 myxoid liposarcoma fusion protein, but not its wild-type counterparts EWSR1 and DDIT3, selectively repressed the transcriptional activity of cell lineage-specific marker genes in multipotent mesenchymal C3H10T1/2 cells." (PMID 22570737, 2012). "A key finding is the absence of DDIT3 rearrangements, which helps differentiate LLT from myxoid liposarcomas, as seen in the present case." (PMID 41246635, 2025). "At the molecular level, they are characterized by the absence of PLAG1 and HMGA2 expression and by the lack of DDIT3 rearrangements, as detected by fluorescence in situ hybridization (FISH), which distinguishes them from lipoblastomas and myxoid liposarcomas." (PMID 41246635, 2025). "Additionally, negative results for DDIT3, CD34, desmin, and PLAG1 support the diagnosis and help exclude myxoid liposarcoma and “adult” lipoblastoma." (PMID 41230282, 2025).
myxoid liposarcoma (continued). "In this study, we showed that the EWSR1-DDIT3 myxoid liposarcoma fusion protein, but not its wild-type counterparts EWSR1 and DDIT3, selectively repressed the transcriptional activity of cell lineage-specific marker genes in multipotent mesenchymal C3H10T1/2 cells." (PMID 22570737, 2012).
hepatocellular carcinoma (83 papers, 2011 to 2025). A malignant tumor that arises from hepatocytes. "Garcinol, a polyisoprenylated benzophenone isolated from Garcinia indica, induces ROS generation and increases the level of both DDIT3 mRNA and DDIT3 protein in human hepatocellular cancer Hep3B cells." (PMID 36497321, 2022). "We were able to confirm that palmitate-induced upregulation of XBP1s and DDIT3 mRNAs was dose-dependently suppressed by co-treatment with oleate in hepatoma cell lines." (PMID 26186544, 2015). "Studies in hepatoma and pheochromocytoma cell lines have shown that the transcription factor encoded by CEBPB (C/EBPβ) promotes expression of DDIT3, another transcriptional regulator that we found to be upregulated in GNS cells." (PMID 23046790, 2012). "REV-ERBα also activates the Ddit3 gene (also known as the CEBP homologous protein) transcription in mouse hepatoma cells, and the REV-ERB-induced gene transcription is functionally inhibited by small heterodimer partner (SHP) nuclear receptor RRE independently." (PMID 38255844, 2024). "In hepatocellular carcinoma, IMD is involved in cell invasion through the ERK1/2-EGR1/DDIT3 signaling pathway." (PMID 37745233, 2023).
liposarcoma (64 papers, 2007 to 2025). A usually painless malignant tumor that arises from adipose tissue. "Notably, the FUS::DDIT3 fusion gene, a common chromosomal translocation in liposarcoma, encodes a transcription factor essential for adipocyte differentiation." (PMID 39229483, 2024). "Minimal staining was observed in cases of dedifferentiated liposarcoma (15%) and solitary fibrous tumor (25%), possibly due to the proximity of DDIT3, MDM2 and STAT6 on chromosome 12." (PMID 33921435, 2021). "Our results suggest a dual, promoting and limiting, role for DDIT3 in the formation of lipoblasts and liposarcoma morphology." (PMID 24790523, 2014). "We further evaluated the role of DDIT3 expression by studying lipoblast formation in cultured liposarcoma cells treated with adipogenic factors." (PMID 24790523, 2014). "The GOT3 liposarcoma cell line carries a strongly amplified DDIT3 gene that results in a constitutive expression of cytoplasmic DDIT3, which was further upregulated upon stress." (PMID 22496745, 2012). "Transfection of primary mesenchymal progenitor and human fibrosarcoma cells with the FUS/DDIT3 fusion protein induces a myxoid liposarcoma phenotype." (PMID 20863376, 2010). "The aim of the present study was to test this hypothesis by investigating the expression of the DDIT3 protein in 3 different subtypes of liposarcoma and in common lipoma." (PMID 24790523, 2014). "DDIT3 induces liposarcoma morphology when ectopically expressed in a human fibrosarcoma." (PMID 24790523, 2014). "Most well-differentiated/dedifferentiated liposarcoma (WDLS/DDLS) cases contain amplified fragments of chromosome 12q13-15, which contains DDIT3." (PMID 39456230, 2024). "Due to this geographic proximity, DDIT3 gene can be amplified in a subset of cases of WDL and dedifferentiated liposarcoma." (PMID 34089125, 2022). "We have analyzed the expression of DDIT3 in 37 cases of liposarcoma (WDLS/DDLS n = 10, MLS/RCLS n = 16, and pleomorphic liposarcomas (PLS) n = 11) and 11 cases of common benign lipomas." (PMID 24790523, 2014). "In terms of genetic abnormalities, MRC liposarcoma is characterized by translocation of chromosomes 12 and 16 (t12;16)(q13;p11), that results in a fusion gene arrangement between FUS and CHOP/DDIT3." (PMID 24216990, 2013). "Here, we show that DDIT3 accumulated largely as a cytoplasmic protein in human fibroblasts and GOT3 liposarcoma cells under ER stress induced by tunicamycin interruption of protein glycosylation." (PMID 22496745, 2012). "This oncogene consists of the NH2-terminal domain of FUS (previously termed translocated in liposarcoma, TLS) fused to the entire codifying sequence of DDIT3 (previously termed CHOP)." (PMID 18596980, 2008). "There was no DDIT3 gene rearrangement or MDM2 gene amplification, and this can be utilized to differentiate this variant of liposarcoma from others." (PMID 40710010, 2025). "The most common entities, well differentiated/dedifferentiated liposarcoma (WDLS/DDLS) and myxoid/round cell liposarcoma (MLS/RCLS), are both characterized by genetic rearrangements that affect the expression of the transcription factor DDIT3." (PMID 24790523, 2014). "Moreover, mice expressing the altered form DDIT3–FUS, created by the in-frame fusion of the FUS domain to the carboxy end of DDIT3 also developed liposarcomas indicating that the activity of the fusion protein FUS-DDIT3 is independent of the chimeric junction." (PMID 18596980, 2008). "Notably, no DDIT3 or FUS gene rearrangements were detected, prompting the classification of the sarcoma as a dedifferentiated liposarcoma." (PMID 39229483, 2024). "However, ectopic expression of DDIT3 in a transgenic mouse model did not develop liposarcoma indicating that in vivo the cellular environment and the cooperation of both domains of the chimeric protein FUS-DDIT3 play a critical role to induce frank malignancy." (PMID 18596980, 2008).
lung carcinoma (64 papers, 2008 to 2025). "DDIT3-rs697221 was identified to have a significant association with the risk of lung cancer under all three genetic models (p < 0.01)." (PMID 35923704, 2022). "He experimentally justified miR-146a as an oncomer since CHOP (DNA damage-inducible transcript 3) was targeted by miR-146a, whose downexpression has been linked to poor prognosis in lung cancer." (PMID 33578944, 2021). "In addition, DDIT3-rs697221 was identified to have a significant association with the risk of lung cancer under all three genetic models (p < 0.01)." (PMID 35923704, 2022). "Consistently, it was previously reported that Ddit3 is involved in ER stress-induced apoptosis of lung cancer cells." (PMID 41228235, 2025). "The study revealed that the reduced expression of DDIT3 in lung cancer shortens the survival time of patients." (PMID 39275122, 2024). "The anti-cancer activity of DMC occurs through promoted expression of ER stress-associated proteins HSPA5, DDIT3, ERN1, ATF6A, ATF6B, CASP4 and CAPS12 in human lung cancer NCI-H460 cells." (PMID 36497321, 2022). "In conclusion, we found that EIF2AK3-rs6750998 was a protective variant against the risk of lung cancer, while EIF2AK3-rs867529, HSPA5-rs391957, and DDIT3-rs697221 were all susceptible variants for the disease." (PMID 35923704, 2022). "BDMC increases ER stress-associated proteins expression such as HSPA5, DDIT3, ERN1, ERN2/IRE-1β, ATF6, ATF6B and CASP4, which results in cell apoptosis in the human lung cancer NCI H460 cell line." (PMID 36497321, 2022). "A similar result was also reported in lung cancer that showed that 20(S)-GRh2 triggers ER stress-related ATF4/DDIT3-induced apoptosis." (PMID 36431966, 2022). "Native musk and synthetic musk ketone can up-regulate IL-24 (interleukin family) and DDIT3 (MAPK signalling pathway) in lung cancer cells." (PMID 27931220, 2016). "This study showed that CTTPPPD can significantly raise the expression of DDIT3, which may inhibit the growth of lung cancer cells and diffusion." (PMID 39275122, 2024). "However, little information is found about the single-nucleotide polymorphisms (SNPs) in EIF2AK3/PERK, HSPA5/GRP78, and DDIT3/CHOP in cancer patients, especially those with lung cancer." (PMID 35923704, 2022). "On the basis of these data and our observations, we hypothesized that musk may induce the growth repression and the apoptosis of lung cancer cell through up-regulating IL-24 and DDIT3 expressions." (PMID 27931220, 2016). "Musk might induce the growth repression and the apoptosis of lung cancer cells through up-regulating IL-24 and DDIT3 expressions." (PMID 27931220, 2016). "Additionally, musk might induce the growth repression and the apoptosis of lung cancer cells through up-regulating IL-24 and DDIT3 expressions." (PMID 27931220, 2016). "This compound increases DDIT3 expression at the gene and protein levels and induces both HSPA5 mRNA and HSPA5 protein in lung cancer 95-D and A549 cells." (PMID 36497321, 2022). "We observed that DDIT3, pERK, and ATF3 mRNA levels were mainly upregulated upon 6-AN treatment in lung cancer cells." (PMID 34827081, 2021). "Because several genes, including DDIT3, TRIB3, and ATF3, were specifically increased due to verteporfin treatment in KRAS-mutant lung cancer cells, we focused on the ER stress pathway." (PMID 33830081, 2021). "DDIT3 cooperates with KAT2A to up-regulate TNFRSF10A and TNFRSF10B expressions and to induce the endoplasmic reticulum stress-mediated apoptosis in lung cancer." (PMID 27931220, 2016). "Furthermore, the up-regulation of DDIT3 (an important ER stress-inducible protein) has been reported to be dependent on ATF3 activation, as it induces apoptotic transcriptional programs through the ATF4–ATF3–DDIT3–TNFRSF10B signaling axis in human lung carcinoma." (PMID 40332279, 2025).
prostate carcinoma (56 papers, 2009 to 2025). A carcinoma that arises from epithelial cells of the prostate gland. "Our finding is consistent with a previous study that showed that monensin induced DDIT3, a key inhibitor of the Wnt signalling pathway, in prostate cancer cells." (PMID 32512820, 2020). "Two of the genes verified in both primary cell lines, Klf6 and Ddit3, are markers of oxidative stress recently reported as upregulated by salinomycin in prostate cancer cells." (PMID 27612428, 2016). "In one such study, GA-DM treatment on prostate cancer cells increased the expression of heat shock 70 kDa proteins (HSP70), C/EBP homologous protein (CHOP, also known as DDIT3), and calpain." (PMID 41304887, 2025). "GATA3 regulation happened in the early stage and the outcome of the prostate cancer at the late stage of tumor development that are related to genes MZF1, SREBF1, PRL, and DDIT3." (PMID 20025723, 2009).
Obesity (52 papers, 2009 to 2026). Accumulation of substantial excess body fat. "Given their relevance in the context of obesity, we next analyzed the expression of the genes encoding ER stress markers ATF4 and C/EBP homologous protein (CHOP) (ATF4 and DDIT3)." (PMID 32512939, 2020).
colon carcinoma (50 papers, 2010 to 2025). "Furthermore, we found that ferrichrome induces apoptosis through a process that is mediated by the JNK-associated induction of DNA damage-inducible transcript 3 (DDIT3) in colon cancer cells." (PMID 27507542, 2016). "Ferrichrome has antitumor potential in colon cancer cells by inducing the expression of DNA damage-inducible transcript-3 (DDIT3), surpassing the efficacy of conventional anticancer drugs such as 5-FU and cisplatin." (PMID 38545201, 2024). "Whereas among the up-regulated genes, there are three pro-apoptosis genes including HRK, TXNIP and DDIT3, which may also helpful to explain how aspirin can induce cellular apoptosis in colon cancer." (PMID 28184026, 2017). "In GANT61-treated human colon carcinoma cells, novel DNA damage-inducible transcripts DDIT3 (GADD153), DDIT4 (REDD1), DDIT2 (GADD45G), PPP1R15A (GADD34) and ATF3 were significantly up-regulated concomitant with the arrest of cells at G1/S." (PMID 20957031, 2010). "Rottlerin, a selective inhibitor of the novel isoforms of protein kinase C δ (PKC δ), significantly induced DDIT3 and NAG-1 expression in HT26 colon carcinoma, but DDIT3 siRNA did not affect rottlerin-induced NAG-1 expression." (PMID 27852055, 2017).
sarcoma (50 papers, 2005 to 2026). A usually aggressive malignant neoplasm of the soft tissue or bone. "In myxoid liposarcoma, which is a type of sarcoma associated with specific translocation DDIT3-FUS or DDIT3-EWSR1, trabectedin proved to be particularly active, and a change in tumor density has often been observed, associated or not with a subsequent reduction in tumor diameters." (PMID 39228518, 2024). "Examples of antibodies serving as surrogate markers of sarcoma-specific genetic aberrations, e.g., fusions, amplifications, and point mutations, include SS18-SSX or SSX, TFE3, SMARCB1, BCOR, MDM2, DDIT3, and PAX3." (PMID 40526340, 2025). "In this region, there are also other genes whose function has been associated with carcinogenesis, including CHOP (DDIT3), SAS and HMGA2, frequently rearranged/overexpressed in human sarcomas, an entire cluster of basic cytokeratins and the HOX C locus genes." (PMID 24085196, 2013). "Here, we show a predominantly cytoplasmic localization of stress induced DDIT3 in human fibroblasts and sarcoma cells." (PMID 22496745, 2012). "Here we show that GOT3 sarcoma cells and normal human fibroblasts accumulate cytoplasmic DDIT3 under tunicamycin and etoposide induced stress conditions." (PMID 22496745, 2012). "DDIT3 is also involved in differentiation of specialized tissues and cells and as an oncogene in sarcomas." (PMID 22496745, 2012). "Loss of Txnip and Ddit3 in SAHA/JQ-treated cells alters the normally cytostatic effects of these inhibitors and results in cell death, suggesting that UPR supports survival in differentiating muscle and sarcoma cells." (PMID 30382078, 2018). "A fusion protein involving the DNA-binding domain of a transcription factor, such as DDIT3 or ERG, and the LC domain of FUS can redirect RNA Pol II activity sufficient to drive Ewing and other sarcomas." (PMID 37690693, 2023). "This translocation is also commonly referred to as FUS-DDIT3, where FUS (fused in sarcoma) corresponds to TLS and DDIT3 (DNA damage inducible transcript 3) represents CHOP." (PMID 32344731, 2020). "In summary, while FUS::DDIT3 binding caused no extreme effects on the SWI/SNF composition, several paralogs as well as PBAF and GBAF subtype-specific components were significantly enriched in FUS::DDIT3-bound SWI/SNF complexes, at levels that may impact the SWI/SNF function in FET sarcoma cells." (PMID 40988026, 2025). "DDIT3 analysis will solve this problem because these sarcoma types do not have DDIT3 fusion." (PMID 39456230, 2024). "Interestingly, FUS::DDIT3 expression unified the cells into overlapping branches regardless of if sarcoma cells were grown in MLS scaffolds or as xenografts in mice, demonstrating that FUS::DDIT3 expression more than microenvironment determines the transcriptional profile of individual tumor cells." (PMID 38671504, 2024).